CD163 (CD163 molecule)
Diseases named in the same sentence as CD163 in open-access papers (continued):
Sharing a sentence is not in itself a finding about the gene and the disease.
colorectal cancer (69 papers, 2007 to 2025). A primary or metastatic malignant neoplasm that affects the colon or rectum. "Tumor microarray samples were positive for tumor-associated macrophages (CD163) and neutrophils (CD66b) in colorectal cancer (n = 97), SCCHN (n = 80), and DLBCL (n = 75)." (PMID 38319147, 2024). "There are many studies on immune cell infiltration in colorectal cancer, including FoxP3+-regulatory T cells, CD66b+ tumor-associated neutrophils, and CD163+ tumor-associated macrophages." (PMID 37232465, 2023). "Clinical data showed the infiltration of CD163 positive macrophages associated with EMT in colorectal cancer metastasis." (PMID 35784347, 2022). "High levels of CD163+ cells were associated with tumor node metastasis stage, depth of infiltration, and lymphatic metastasis in 197 patients with colorectal cancer from China." (PMID 36686729, 2022). "The macrophage-associated molecule CD163 has been reported as a prognostic biomarker in different cancer types, but its role in colorectal cancer (CRC) is unclear." (PMID 32824692, 2020). "We previously demonstrated that CCL4 tumor levels have a positive correlation with the M2 marker (CD163) associated with a poor clinical outcome of colorectal cancer and lower cumulative survival than patients with low CD163 expression." (PMID 32499779, 2020). "CD163 was expressed by tumor cells in 48% of breast and 20% of colorectal cancer patients and was significantly associated with advanced tumor stages and poor survival." (PMID 28881654, 2017). "Macrophage-specific antigen CD163 expression in tumor cells is reported in breast and colorectal cancers and proposed being caused by macrophages-cancer cell fusion in tumor stroma." (PMID 26585897, 2015). "Interestingly, preoperative irradiation in patients with colorectal cancer was also significantly associated with the presence of CD163+ tumor cells, suggesting a possible connection between X-rays and induction of cell fusion." (PMID 37427108, 2023). "Infiltration of CD163+ tumor-associated macrophages, FoxP3+-regulatory T cells, and CD66b+ tumor-associated neutrophils in colorectal cancer tissues may be related to the differentiation of tumor cells." (PMID 37232465, 2023). "The number of CD163+ tumor-associated macrophages, FoxP3+-regulatory T cells, and CD66b+ tumor-associated neutrophils in colorectal cancer tissues was different, and the level of CD163+ tumor-associated macrophages was the highest while the level of FoxP3+-regulatory T cells was the least." (PMID 37232465, 2023). "Another research work has demonstrated that the CD86/CD163 ratio may be used for individualized assessment of recurrence and mortality risk in colorectal cancer patients." (PMID 38136305, 2023). "However, some studies showed that increased CD163+ TAM prevalence was associated with improved clinical outcomes in colorectal carcinoma." (PMID 35053472, 2022). "This study investigated the association between Helicobacter pylori (H. pylori) infection and the expression of CD163+ and CD86+ tumor-associated macrophages (TAMs) in colorectal adenoma (CRA) and colorectal cancer (CRC) tissues." (PMID 41395618, 2025). "Protein levels of SIRPα and CD163 were additionally confirmed by IHC in tumor samples from patients with colorectal cancer, SCCHN, and DLBCL." (PMID 38319147, 2024). "The TAM markers CD68 and CD163 were analyzed by multiplex fluorescence immunohistochemistry and digital image analysis on tissue microarrays of 1720 primary colorectal cancers." (PMID 38407700, 2024). "Another study showed that colorectal cancer cells promote the polarization of macrophages to the M2 phenotype characterised by surface marker CD163, mediated by CCL2 and ICAM1." (PMID 37108548, 2023). "By combining the prognostic information of anti-tumoural CD8+ lymphocytes and tumour supportive CD68+CD163+ macrophages in colorectal cancer we generated a signature of immune activation (SIA)." (PMID 36724681, 2023).
colorectal cancer (continued). "Expressions of CD68, CD86 and CD163 were investigated by immunohistochemistry (IHC) and immunofluorescence (IF), and the correlation between the expression of CD86 and CD163 was calculated in colorectal cancer tissues from 64 CRC patients." (PMID 34964155, 2022). "It is well known that CD163 can enhance the migration and invasion of colorectal cancer cells and is related to the poor prognosis of patients." (PMID 36195882, 2022). "For example, a high CD163+/CD68+ ratio in the infiltrative margin of the tumor suggests a poor prognosis for the colorectal cancer patients." (PMID 36195882, 2022). "Using multispectral immunofluorescence it was demonstrated that CD163+ cells have immunosuppressive phenotype in 17 patients with colorectal cancer who underwent resection of primary and liver metastases." (PMID 36686729, 2022). "As validation, we found a small population of cells co-expressing α-SMA and CD163 in the stromal compartment of anaplastic thyroid cancer, colorectal cancer and stomach cancer through confocal mIF imaging." (PMID 36333338, 2022). "A recent study indicates that CMTM6 is expressed on CD8+ T cells and CD163+ M2 macrophages in colorectal cancer tissues." (PMID 34680324, 2021). "In colorectal cancer patients, CD163 expression was found to be decreased in the classical and total subpopulations." (PMID 35237501, 2021). "We investigated the stromal CD86+TAM/CD163+TAM (CD86/CD163) ratio as a novel prognostic biomarker for stage II-III colorectal cancer (CRC)." (PMID 34512652, 2021). "A recent study has consistently shown that the ratio of CD163+/CD68+ macrophages in tumor tissue is an independent prognostic factor for survival in patients with colorectal cancer." (PMID 36860286, 2021). "The purpose of this study was to investigate the effect of CD163-positive M2 macrophages on lymph node metastasis in colorectal carcinoma." (PMID 33781288, 2021). "Cellular subpopulations within the colorectal tumor microenvironment (TME) include CD3+ and CD8+ lymphocytes, CD68+ and CD163+ macrophages, and tumor buds (TBs), all of which have known prognostic significance in stage II colorectal cancer." (PMID 32435699, 2020). "In colorectal cancers, high expression of CD163 on TAMs was found in TME, resulting in an increased number of CD4+ lymphocytes that contributed to up-regulate the PD-1 expression." (PMID 32756500, 2020). "Similar findings were reported for colorectal cancer patients demonstrating that CD163 expression in tumor cells was correlated with a significantly decreased cumulative survival and local recurrence-free survival." (PMID 30736482, 2019). "A significant number of macrophages were also found infiltrating human colorectal cancers (mean = 36.1±3 cells/0.01 mm2, range = 17.2–50.2) in the 11 tumors assessed as determined by immunohistochemical staining for CD163." (PMID 24866282, 2014). "Furthermore, these three genes-TLR2, IFNG, and CD163-are abundantly expressed in colorectal cancer (CRC) tumor tissues." (PMID 41300749, 2025). "The infiltration of CD163+ macrophages, indicative of an immunosuppressive M2 phenotype, varied among colorectal cancer (CRC) subtypes, being most prevalent in CMS1 and CMS2/3 (87.0% vs. 61.0%), less prevalent in CMS4, and associated with an intermediate-to-high immunoscore." (PMID 40594059, 2025). "Our observations that CD163+ (M2) macrophages are more numerous in K17-positive intratumoral areas are consistent with previous studies in colorectal cancer and align with work depicting CD163 CD+ T cells as promoter of biologic aggression in pancreatic cancer." (PMID 38730319, 2024). "However, for gastrointestinal tumors, it has been shownthat CD163 can be a marker of good prognosis, particularly in esophageal cancer and colorectal cancer." (PMID 36694901, 2022). "CD163 was identified as a good predictor of pre-metastatic status of colorectal cancer." (PMID 36686729, 2022).
colorectal cancer (continued). "Finally, protein–protein interaction networks and pathway enrichment analysis were used to investigate the relationship between CD163 and colorectal cancer." (PMID 36551651, 2022). "In colorectal carcinoma, strong infiltration of intraepithelial CD163+ macrophages was correlated with unfavorable clinicopathological features, such as lymph node invasion; however, in endometrial cancer, stromal TAMs rather than tumor core TAMs promoted lymph node metastasis." (PMID 33178603, 2020). "Based on cell fusion theory and the assumption that the macrophage–cancer cell fusion creates hybrids expressing phenotypic characteristics of macrophages, we reported in previous studies that the macrophage-specific marker, CD163, was expressed in breast and colorectal cancers." (PMID 26585897, 2015). "CD163 is a macrophage/histiocyte associated scavenger receptor, which has not been analyzed in colorectal cancer thus far." (PMID 18047662, 2007). "Interestingly, in colorectal cancers (CRCs), CD163-positive M2-like macrophages exhibit anti-tumor activity in tumors with low levels of the anti-phagocytotic marker CD47 and positively correlate with the expression of CD68, which predicts increases in long-term survival." (PMID 38255296, 2024). "Multiplex immunofluorescence (mIF) quantification revealed significantly increased densities of both CD68+CD86+ and CD68+CD163+ TAMs, and a higher CD68+CD163+/CD68+CD86+ ratio in colorectal cancer (CRC) (all P < 0.001)." (PMID 41395618, 2025). "Our SPP1+ TAM population also expressed CD68 but had low expression of CD206 and CD163, which differed slightly from another study of SPP1+ macrophages in colorectal cancer that had high CD206 expression." (PMID 39075108, 2024). "CD163+ TAMs induce the epithelial-to-mesenchymal transition (EMT) and thereby enhance colorectal cancer cell migration and invasion." (PMID 38473429, 2024). "We used multiple immunofluorescence techniques to detect the expression of CD19, CD163, C-kit, CD68, NOS2, mast cell tryptase, and CD16 markers in colorectal cancer tissues and surrounding normal tissues on the same slide." (PMID 35646079, 2022). "Immunohistochemical staining was used to detect the macrophages infiltration (CD68 and CD163), epithelial–mesenchymal transition (EMT) markers (E-cadherin and Vimentin) expression in serial sections of human colorectal cancer (CRC) specimens." (PMID 30927925, 2019). "Here, we profiled macrophages in a series of 150 colorectal cancer (CRC) cases by immunohistochemistry, using CD68 as a macrophage lineage marker, CD80 as a marker of pro-inflammatory macrophages, and CD163 as a marker of anti-inflammatory macrophages." (PMID 31481956, 2019). "For example, in colorectal cancer, the abundance of macrophages expressing high levels of CD86 and low levels of CD163 could be used as predictor of prognosis." (PMID 38140397, 2023). "Moreover, sequentially immunostained sections of colorectal carcinoma (n = 5) and matched normal mucosa showed decreased expression of CIITA in CD163+ macrophages compared to normal tissue." (PMID 34680345, 2021). "In the results of phenotype analysis by flow cytometry, colorectal cancer cells expressing higher MTA1 promoted the polarization of macrophages to the CD206+ phenotype while inhibiting CD163+ polarization without affecting the polarization of the CD86+ phenotype." (PMID 35350571, 2022). "In an independent cohort of N = 287 colorectal cancer patients, we show that hot, cold and excluded topographies for effector lymphocytes (CD8) and tumor-associated macrophages (CD163) alone are not prognostic, but that a bivariate classification system can stratify patients." (PMID 30179157, 2018). "In addition to providing mechanistic insights, CAFs and CD163+ macrophages (M2) may also prove to be potential prognostic predictors; since expressions of CAF and M2 macrophage markers are correlated with poor prognosis in colorectal cancer and oral squamous cell carcinoma." (PMID 34336660, 2021).
gastric cancer (64 papers, 2013 to 2026). A primary or metastatic malignant neoplasm involving the stomach. "Tumor-associated macrophages strongly express CD163, and the density of these macrophages negatively influences gastric cancer growth and metastasis." (PMID 38504975, 2024). "CD163 and Stabilin-1, as M2-associated markers, were used to localize macrophages in gastric cancer tissues." (PMID 32226513, 2020). "However, the recent report suggests that an increased density of CD68+CD163+ macrophages in tumor tissues is in fact associated with up-regulated immune signaling and improved survival of patients with gastric cancer." (PMID 35525858, 2022). "Clinically, high expression of CXCL5 in gastric cancer samples was associated with the high infiltration of CD163 positive macrophages and CD206 positive macrophages, and patients with high expression of CXCL5 presented lower overall survival (OS) rates than those with low expression of CXCL5." (PMID 36151545, 2022). "Similarly, CD163(+) TAMs were associated with poor OS and increased microvessel density in gastric cancer." (PMID 34633990, 2021). "CD163+ tumor-associated macrophages infiltration positively correlates with angiogenesis, lymph angiogenesis, reduced overall survival rate, and recurrence-free survival in gastric cancer." (PMID 34458140, 2021). "The CD163+ and CD11b+ tumor-associated macrophages (TAMs) have been associated with a poor prognosis for gastric cancer patients, and the increased number of M1 macrophages may be associated with a better OS for gastric cancer patients 42,43." (PMID 31892988, 2020). "Besides, more CD163 positive macrophages and CD163 expressing gastric cancer cells are associated with tumor invasion and poor prognosis." (PMID 29152078, 2017). "According to our results, CD16 macrophages were expressed in gastric cancer and marginal tissues, whereas CD163 macrophages were highly expressed in gastric cancer and lowly expressed in marginal tissues, suggesting that the tumor-associated macrophages were closely correlated with gastric cancer." (PMID 32332633, 2020). "In the subgroup analysis of prognosis prediction for diffuse gastric cancer, CD8+TILs, CD163+TAMs are closely related to gastric cancer DFS and OS." (PMID 40636693, 2025). "Studies have reported that immunosuppressive CD163+ M2 macrophages are prevalent in peritoneal metastatic tissues and ascites from gastric cancer patients, suggesting their potential role in dampening the efficacy of ICI treatments." (PMID 40738981, 2025). "The increased density of CD163-positive TAMs, along with the high CD68 expression, was also associated with upregulated immune signaling and improved outcomes for gastric cancer." (PMID 38255296, 2024). "In particular the percentage of CD163+ M2 macrophages increased in gastric cancer samples, showing that M2 macrophages are an integral part of the gastric microenvironment during carcinogenesis." (PMID 38422751, 2024). "We first verified that circGLIS3 and M2 macrophages (CD163 +) were highly expressed in gastric cancer tissues compared with adjacent normal tissue." (PMID 38459513, 2024). "FC/ICFC analysis with fresh gastric cancer samples (FDU‐ZSH EXPC Arm C) also validated that VISTA+ TAMs exhibited significantly higher expression of M2‐like marker CD163 and CD206, as well as M1‐like marker human leukocyte antigen (HLA)‐DR and CD11c." (PMID 38356419, 2024). "Using the Cancer Genome Atlas (TCGA) database of EBV-positive versus EBV-negative samples of gastric carcinoma 24, we found increased levels of CD163 mRNA in EBV-positive samples." (PMID 39267775, 2024). "M2-polarized macrophages identified by the CD163 molecule were substantially expressed in gastric cancer and lowly expressed in marginal tissues, implying that macrophage polarization is intimately related to gastric cancer." (PMID 36825088, 2023).
gastric cancer (continued). "The correlation analysis between macrophage polarization status and clinicopathological stage in gastric cancer showed that the density of CD163-positive macrophages was higher in patients with TNM III–IV compared with patients with TNM stage I–II." (PMID 34458140, 2021). "To validate these findings, we carried out immunohistochemistry (IHC) to detect CD163 and FoxP3 proteins in our gastric cancer specimens." (PMID 34760687, 2021). "It was also demonstrated that CD163+ TAMs were involved in promoting the peritoneal dissemination of gastric cancer via IL-6 secretion." (PMID 33163402, 2020). "The protein expression of CD16 and CD163 in 90 gastric cancer tissues and 30 margin tissues was detected by immunohistochemistry." (PMID 32332633, 2020). "In gastric cancer, the clinical outcome was associated with high number of tumor‐associated macrophages (CD68+CD163+) and their proximity to tumor cells." (PMID 33072322, 2020). "For instance, in gastric cancer CD163+ TAMs are significantly correlated with increased microvessel density and poor overall survival." (PMID 32752088, 2020). "Findings in this study also found that, CD163 expression in gastric cancer was significantly higher than that in marginal tissues, and the expression of HP-positive CD163 (75.38%) in gastric cancer was also higher than that in HP-negative tissues (52.00%)." (PMID 32332633, 2020). "Subgroup Cox regression analysis in patients with esophageal cancer showed that high infiltration of CD68+ macrophages was prognostic in the unadjusted model whereas high infiltration of both CD68+ and CD163+ macrophages were prognostic in gastric cancer." (PMID 33194593, 2020). "High density of CD163+ (CD206–) TAMs with concurrent high CD68 expression was reported to be associated with upregulated immune signals and improved patient survival in gastric cancer." (PMID 33163402, 2020). "Corosolic acid inhibits STAT3, which is an oncogene increased in several human malignancies and an important regulator of CD163 in gastric cancer cells." (PMID 32752088, 2020). "MiR-4262 targeted CD163 to inhibit cell proliferation and invasion in gastric cancer, and low miR-4262 level predicts poor prognosis." (PMID 32681092, 2020). "In summary, our data demonstrate that CD163 is a novel predictor to evaluate gastric cancer immune status and tumor prognosis." (PMID 29152078, 2017). "Totally, all these findings confirmed that STAT3 was an important regulator of CD163 in gastric cancer cells." (PMID 29152078, 2017). "Since CD163 is widely expressed in TAM, so understanding the expression and regulatory mechanism of CD163 in gastric cancer is important for gastric cancer therapy based on CD163." (PMID 29152078, 2017). "In the recent study, we evaluate the expression of CD163 in gastric cancer tissues, and explore its function and regulatory mechanism in gastric cancer cell lines." (PMID 29152078, 2017). "Although study had found CD163 was increased in Helicobacter pylori infection, the expression of CD163 in gastric cancer is still unclear." (PMID 29152078, 2017). "Subsequently, we find CD163 is high expression in some gastric cancer cells especially in muscle layer invaded cells." (PMID 29152078, 2017). "We also find various immune molecules which are correlated with CD163 in gastric cancer tissues and cell lines have positive staining in the cancer cells of clinical sample." (PMID 29152078, 2017). "In an effort to examine the potential function of CD163 in gastric cancer cells, genes which were co-expressing with CD163 in 37 gastric cancer cell lines and 381 gastric cancer tissues were analyzed (correlation coefficient >3.5)." (PMID 29152078, 2017). "To explore the potential function of CD163 in gastric cancer cells, we compared the expression of CD163 in cancer cells located in gastric mucosa with that invaded into muscle layer from same patients." (PMID 29152078, 2017).